DUSP1 (dual specificity phosphatase 1)
Diseases named in the same sentence as DUSP1 in open-access papers (continued):
Sharing a sentence is not in itself a finding about the gene and the disease.
cancer (continued). "In support of this conclusion, cancer cells that overexpress DUSP1 are resistant to chemotherapy and Fas ligand-induced apoptosis, whereas reduction of DUSP1 levels using a small interfering RNA enhances sensitivity to these agents." (PMID 24409315, 2014). "DUSP1 has been demonstrated to sensitize cancer cells to cisplatin-induced apoptosis and overexpression of DUSP6 in estrogen receptor-positive breast cancer cells confers resistance to tamoxifen." (PMID 25568665, 2014). "Over the past years, differences in DUSP1 gene expression have been reported in various types of cancers." (PMID 23986905, 2013). "However, these cells showed decreased expression of inflammatory markers CD69, FOS and DUSP1 in cancer patients, thus indicating a less active inflammatory profile." (PMID 40340807, 2025). "Although DUSP1 regulated MAPKs activity in cancer, its expression varies in a variety of cancers." (PMID 41158869, 2025). "Soybean intake is significantly correlated with methylated DUSP1 in ER and PR-negative patients, and irregular menstruation is correlated with methylated DUSP1 in ER and PR-positive patients, indicating that environmental factors likely impact DUSP1 expression in cancer." (PMID 41158869, 2025). "DUSP1, a bispecific phosphatase regulating MAP kinase activity, has been associated with various cancers, but its role in GC remains unclear." (PMID 40489463, 2025). "Moreover, DUSP1 has been found to regulate DNA repair mechanisms, promoting the survival of cancer cells following radiation-induced DNA damage." (PMID 41158869, 2025). "We further discuss the potential for pharmacologically targeting DUSP1 in various human cancers." (PMID 41158869, 2025). "Indeed, we were only able to generate heterozygous deletions of DUSP1 gene, highlighting its essential role in this cancer type." (PMID 38951654, 2024). "In contrast, the inhibition of one of the phosphatidylinositol-3-kinase (PI3K) signaling pathways important for cancer therapy in murine macrophages resulted in the increased expression of DUSP1 and IL-10, and promoted the anti-inflammatory properties of macrophages." (PMID 38139370, 2023). "Additionally, a query of a database generated recently by a systematic study of druggable genes in cancer revealed that DUSP1 has the highest potential as a drug target among all DUSPs." (PMID 35999349, 2022). "According to the findings above, we deduced that DUSP1 might act as an essential factor of skeletal muscle atrophy in patients with cancer cachexia." (PMID 36387242, 2022). "Activity of Dual Specificity Phosphatase 1 (DUSP1) downregulate L1 in cancers cells." (PMID 34680956, 2021). "The authors concluded that cancer cell proliferation was reduced in the presence of miR133b-loaded exosomes, both in vivo and in vitro, and attributed its anti-oncogenic properties to upregulation of Dual Specificity Phosphatase -1 (DUSP-1)." (PMID 33803085, 2021). "Interestingly, we found that the TAM1 and TAM3 cells also show high expression levels of multiple oncogenes, such as DUSP1, IER2 and NAMPT, which have been implicated in cancer progression." (PMID 34805184, 2021). "In addition, it has been reported that DUSP1 inhibits cell migration, invasion, and metastasis in other cancer types." (PMID 33800291, 2021). "One aspect of cancer biology in which DUSP1/MKP-1 does appear to play an important role is in the response of normal and cancer cells to a range of chemical and physical insults including modalities used in cancer chemotherapy." (PMID 30401534, 2019). "Several studies have supported a context-dependent function of DUSP1 in cancer." (PMID 31086176, 2019). "Finally, although DUSP1/MKP-1 has been widely studied as a modulator of drug responses in cancer chemotherapy (see Section 2.1.3) less attention has been paid to the ERK-specific MKPs." (PMID 30401534, 2019). "Previous studies revealed that DUSP1 may play opposing roles in different cancer types or different stages of cancer." (PMID 31767833, 2019).
cancer (continued). "The mechanism and function of DUSP1 in cancers varies dependent on the cancer type." (PMID 29558404, 2018). "Dysregulation of MKPs, such as DUSP1/MKP-1, mediates chemoresistance in cancer cells." (PMID 29100381, 2017). "This inhibition effect could be attenuated by knocking down DUSP1 in M38 cells which implies a protective role of DUSP1 in CD8+ T cells mediated cytotoxicity to cancer cells." (PMID 27227569, 2016). "DUSP1 also plays a protective role in cancer cells after radiation." (PMID 27227569, 2016). "DUSP1 promotes the chemoresistance of many chemo‐agents in various cancers." (PMID 27227569, 2016). "The function of DUSP1 in other cancers' immune environment need to be further explored." (PMID 27227569, 2016). "Altered expression of DUSP1/MKP1 has been reported in different human cancer." (PMID 24886454, 2014). "Thus, targeting DUSP1 in vivo led to suppressed angiogenesis and cancer cell proliferation, and enhanced gemcitabine-induced apoptosis." (PMID 24409315, 2014). "Also localized in this MCR, STK10 and DUSP1, that shared similarity with a protein 1 kinase domain, had a strong expression in the placenta; CNAs of these genes have been reported to occur in cancer." (PMID 22253721, 2012). "Furthermore, DUSP1 may support both protumoural and antitumoural activities depending on the type of cancer, as it has, for example, a clear antitumoural role in NSCLC and HCC and a protumoural role in OC and BC." (PMID 40943262, 2025). "Finally, Cheng and colleagues found that the administration of baculovirus-derived recombinant DUSP1 reduced the level of ERK1/2 phosphorylation in cell lines from different types of cancer (GC-7901, MCF-7, HeLa, A49, PC-2, and HepG2) and decreased the proliferation of HeLa cells." (PMID 40943262, 2025). "Several lines of evidence seem to indicate that DUSP1 may support cancer onset and development." (PMID 40943262, 2025). "Studies have found that the absence of DUSP1 expression is associated with certain cancers." (PMID 40489463, 2025). "Moreover, GSEA revealed that AREG, ATF3, ZFP36, and DUSP1 may regulate OSA via inflammation and contribute to OSA-related cancer risk." (PMID 35372438, 2022). "However, it is reported that a DUSP1 blockade might provide a novel chemotherapeutic strategy to sensitize cancer cell death." (PMID 35627105, 2022). "Finally, to obtain further insights into potentially relevant mechanisms in OSA pathogenesis, we used GSEA to analyze the signaling pathways related to AREG, ATF3, ZFP36, and DUSP1, and found that all four markers were related to inflammation and cancer-related pathways." (PMID 35372438, 2022). "Thus, the deleterious consequences of DUSP1 overexpression are likely cancer specific." (PMID 24409315, 2014). "However, the antitumor effects of DUSP1 may well be related to the cancer type and the stage of the disease." (PMID 21547253, 2011). "Consistent with the observations in vitro, the mRNA levels of c-Jun target genes, Cxcl1, Dusp1, Fgb, and Ppp1r15a, regulated by ALDOA were significantly decreased in the cancer tissues of AAV8-shAldoa mice compared with AAV8-GFP mice." (PMID 40708574, 2025). "This overexpression of DUSP1 blocks the phosphorylation of ERK1/2 and mediates anti-cancer activity in both in vitro and in vivo models." (PMID 40943262, 2025). "In this comprehensive review, we mainly focus on typical DUSP1/MKP1, a founding member of DUSPs, and characterize its potential role in cancer." (PMID 41158869, 2025). "PAX1 activated a group of phosphatases, including DUSP1, 5, and 6, and inhibited EGF/MAPK signaling to suppress cancer development." (PMID 39304838, 2024). "The best characterized DUSP6 inhibitor molecule BCI ((E)-2-Benzylidene-3-(cyclohexylamino)-2,3-dihydro-1H-inden-1-one), is a semi-allosteric inhibitor of both DUSP1 and 6 that phenocopies genetic DUSP6 inhibition in several cancer models." (PMID 38886591, 2024).
cancer (continued). "In summary, our work demonstrates the role of two relevant genes (DUSP1 and SOX2), in a rare type of cancer such as SG-SCC." (PMID 38951654, 2024). "BCI is a semi-allosteric inhibitor of both DUSP1 and DUSP6 and several studies have demonstrated that BCI phenocopies genetic DUSP6 inhibition in cancer." (PMID 38886591, 2024). "DUSP1, as an important member of the Mitogen-activated protein kinase (MAPK) gene family, is considered a tumor suppressor and a regulator of cancer-related inflammation." (PMID 38443340, 2024). "The results revealed five cancer-promoting genes (AXL, SCG5, VOPP1, DCBLD2, DRAM1), and three tumor suppressor genes (DUSP1, AQP5, BLNK)." (PMID 37925175, 2023). "The eight mRNAs selected for further analysis, AXL, SCG5, VOPP1, DCBLD2 and DRAM1 are cancer-promoting genes, DUSP1, AQP5 and BLNK are cancer suppressor genes." (PMID 37925175, 2023). "The expression of DUSP1, AQP5, and BLNK in malignant tumors of the oral region was significantly lower than in normal tissues, according to the TCGA database." (PMID 37925175, 2023). "DUSP1, a crucial regulator of MAPK signalling pathways, has shown promise as a combination target in the context of cancer progression." (PMID 38031960, 2023). "Dual specificity protein phosphatase 1 (DUSP1), is involved in the negative regulation of cell proliferation and suppression of inflammatory responses, and its activity downregulates LINE-1 in cancer cells." (PMID 37546391, 2023). "Of note, AREG, ATF3, DUSP1, and ZFP36 were all related to cancers or pathways in cancer, and numerous studies have reported a role for these genes in different tumors." (PMID 35372438, 2022). "BCI is a small-molecule that acts as a dual-inhibitor of DUSP1 and DUSP6, exerting anti-tumorigenic activity in a wide range of cancer models." (PMID 36589747, 2022). "Given the documented evidence of DUSP enzymes having pro‐oncogenic activities in various cancers, we have investigated the therapeutic potential of BCI, a dual DUSP1/6 inhibitor, across a range of NB cell lines." (PMID 35478300, 2022). "However, to date, the role of DUSP1 in muscle atrophy of cancer cachexia remains unclear." (PMID 36387242, 2022). "Consistently with DUSP1 effects on MAPK activity, the ERK pathway is one of the major oncogenic signals in human cancers because its activation leads to an increase in proliferation, invasion, and metastasis." (PMID 33800291, 2021). "Recent studies considered DUSP1 as an anticancer target molecule to modulate the apoptosis and autophagy signaling of over-activated MAPK pathway in cancer cells." (PMID 33244087, 2020). "At present, there have been many studies of DUSP1 and DUSP6 in cancer, but far fewer studies on the relationship between these proteins and the development of hair follicles." (PMID 28125615, 2017). "All six pre-specified cancer genes (IL8, IL1, SAT, OAZ1, DUSP1 and S100P) were up-regulated in cancer versus control patients with from nearly twofold to over threefold higher levels (p<0.01 for all based on delta Cq values)." (PMID 27411053, 2016). "Similar to DUSP1, DUSP6 is upregulated in HER2+ carcinomas; however, little is known about its expression in normal mammary tissue." (PMID 26859151, 2016). "Next, we investigated in SKP2/N-RasV12 lesions the levels of tumor suppressors that have been shown to be inactivated in cancer via SKP2-dependent proteolysis, including p27, p57, Dusp1, and Rassf1A, by immunohistochemistry." (PMID 25537506, 2015).
cancer (continued). "On the other hand, the genes upregulated after G9a depletion include several tumor suppressor genes like dual specificity phosphatases (DUSP1, DUSP3 and DUSP5), which mediate MAP kinase dephosphorylation and are commonly repressed in many cancer cells." (PMID 25115793, 2014). "Among these, LAMA2, DUSP1, PRKAR1B, and APP were downregulated while the rest of the genes were upregulated in cancer as compared to normal cervical samples in the samples used for microarray." (PMID 24403257, 2013). "Another category of genes expressed during this time period are the dual specificity phosphatases, DUSP1, DUSP5, and DUSP7, which are involved in MAP/ERK signaling and can play roles in development or cancer." (PMID 23505351, 2013). "DUSP1 expression can be induced by active p38 and JNK depending on the cell context, and it is often upregulated in cancer." (PMID 23060802, 2012). "The fact that both meta-A and meta-B gene sets share DEK, DUSP1 and ITGA6 in common indicates that all three cancer-related genes are more important to look at among all others." (PMID 18605998, 2008). "IL8, SAT, DUSP1, IL1b, HA3, S100P, and OAZ1, which are related to cancer." (PMID 38522008, 2024). "Future work may involve longitudinal studies of Dusp1 levels in diverse populations most affected by CVD and cancer disparities." (PMID 39718832, 2024). "In brief, DUSP1, ZFP36, SLC2A3, HMGB1, STAT3, MT3, and ALOX5 were all FRGs that might be involved in cancer development and immune regulation." (PMID 36131791, 2022). "DUSP1 was upregulated in BLCA tissues and inhibited cancer cells proliferation." (PMID 35125116, 2022). "Combined with findings from our current study, we speculate that AREG, ATF3, DUSP1, and ZFP36 may serve as a bridge between cancer and OSA." (PMID 35372438, 2022). "Overall, these data highlight the risk of using an inhibitor such as BCI as supposedly specific DUSP1/6, without understanding its full range of targets in cancer cells." (PMID 35478300, 2022). "But the expression and function of DUSP1 in muscle atrophy during cancer cachexia has not been reported." (PMID 36387242, 2022). "In addition, a number of studies have relied on ectopic overexpression of DUSP1/MKP-1 in normal and cancer cell lines to study its possible role in modulating oncogenic signalling." (PMID 30401534, 2019). "DUSP1 and DUSP2 were down-regulated in several types of cancers." (PMID 29422643, 2018). "In addition, DUSP1 expression was much lower in more malignant tumors (AJCC stages III and IV) than in tissues from less malignant tumors (AJCC stages I and II)." (PMID 28129656, 2017). "Pathway analysis of the 50 gene NIT signature revealed enrichment for MAPK signalling (DUSP1, JUN, NR4A1 and FOS), cancer specific (COX-2, PGE2, JUN and FOS), apoptosis induction (FOS and JUN) and genomic reformatting following (brain) ischaemia (EGR1 and JUN) pathways." (PMID 27384960, 2016). "The modulation of DUSP1 activity may thus be included among the possible therapeutic strategies in a subset of cancers but not in others." (PMID 40943262, 2025). "Given that DUSP1 inhibition may worsen underlying autoimmune conditions and neurological disorders, when developing clinical trials, it must be noted that cancer patients with these comorbidities may not be ideal candidates for DUSP1 targeting." (PMID 41158869, 2025). "In addition, we also found that DUSP1 and DUSP2 were down-regulated in several types of cancers." (PMID 29422643, 2018). "The results showed that RGS2 and DUSP1 were significantly expressed in the cell population, and three model genes, CXCR4, SLCO2A1, and FNDC1, were not in the cluster, indicating that the two model genes that were significantly expressed could be used as marker genes of cancer." (PMID 36591293, 2022). "Indeed, DUSP1, as a negative modulator of MAPKs, has been shown to be a key player in several physiological and pathophysiologic processes, such as the immune response, metabolic diseases, and different types of cancers." (PMID 30647800, 2018).
cancer (continued). "Therefore, induction of DUSP1 and DUSP2 might be a therapeutic strategy for treating cancer." (PMID 29422643, 2018). "This leaves the possibility that DUSP1 inhibition by BCI is still contributing to the JNK activation in KELLY and IMR‐32 cells, as it does in other cancer cell types, but this is not the cytotoxic effector of BCI." (PMID 35478300, 2022). "This analysis also revealed a number of epigenetic oncogenes (KDM1A, HDAC1, TDG) and tumor suppressors (KAT2B, PRDM5, DUSP1, EYA4) which did not correlate significantly with any of the others, suggesting that these may affect cancer DNAm patterns independently of each other." (PMID 26169266, 2015). "Instead, recent studies have shown that GCs initiate a survival signal in ERα-negative breast epithelial (MCF10A) and cancer (MDA-MB-231) cells via up-regulation of pro-survival genes, such as serum and glucocorticoid-regulated kinase 1 (SGK1) and dual specificity phosphatase 1 (DUSP1)." (PMID 23814048, 2013).